CDK1 (cyclin dependent kinase 1)
Diseases named in the same sentence as CDK1 in open-access papers (continued):
Sharing a sentence is not in itself a finding about the gene and the disease.
cancer (continued). "To further evaluate the expression of CDK1 in human cancers, we used the TIMER2 database to analyze the expression of CDK1 in different types of TCGA tumors." (PMID 36090896, 2022). "Some members of CDK family including CDK1, CDK2, CDK4 and CDK6 have been reported to be involved in the regulation of cell cycle, thus participating the development and progression of cancer." (PMID 35517403, 2022). "Some cancer-related proteins were consistently changed in MNNG/HOS cells after knocking down MCM8, including the downregulation of P-Akt, CDK1, and CDK6, as well as the upregulation ofMAPK9." (PMID 33828075, 2021). "We found that FDI-6 and FOXM1 shRNA impaired Olaparib-induced expression of CDK1, CCNA1, CCNB1, and CDC25B to inhibit the mitosis of cancer cells." (PMID 34880209, 2021). "Relative to normal colorectum tissue, gene expression of CDK-1 and CDK-4 were up-regulated in all major forms of cancer with high mRNA expressions observed in CRC." (PMID 33732631, 2021). "Dual inhibition of CDK1 and HSP90 significantly increases apoptosis and synergistically inhibits cancer cell viability." (PMID 34686682, 2021). "In summary, combined targeting of CDK(s) (CDK1 or CDK4/6) and HSP90 remarkably inhibits the expression level of HIF1α and shows promising anti-cancer efficacy with therapeutic potential." (PMID 34686682, 2021). "CDK1 is the only CDK of critical importance in the process of cell proliferation, and the abnormal expression of CDK1 has been observed in a variety of primary cancers." (PMID 34093198, 2021). "Based on The Cancer Genome Atlas (TCGA) and The Human Protein Atlas (THPA) databases, CDK1 and CDC20 were upregulated in LUSC at the mRNA and protein levels." (PMID 34307447, 2021). "Computational analysis and in vitro assays identified CDK1, one of the most promising lethal targets for KRAS-mutant cancer, as a target of miR-34c-3p." (PMID 32948832, 2021). "Other interactors include Rap1-interacting adapter molecule (RIAM; also known as APBB1IP), deleted in liver cancer 1 (DLC1), and cyclin dependent kinase 1 (CDK1) (see poster and Box 1 for more details)." (PMID 34708856, 2021). "If CDK1 was knockdown, the pathway of DEPDC1B would be inhibited or blocked, which was consistent the results in other cancers." (PMID 34032605, 2021). "It was also reported that the indole-containing hybrid compounds were shown inhibitory activity on CDK1 with IC50 1.14 μM, significant antiproliferative activities on various kinds of cancer cell lines." (PMID 34930409, 2021). "VEGFA, PTEN, PIP5K1A, CDK1, and CCND1 in the panel are key factors involved in the PI3K/AKT pathways important for cancer survival and metastasis." (PMID 33363151, 2020). "Butyrolactone I is a poly-CDK modulator significantly inhibiting CDK1 and CDK5 and has been considered as an anti-cancer drug candidate." (PMID 32054125, 2020). "Taken together the underlying mechanisms for the observed markedly promoted growth inhibition and apoptosis induction by combined therapy can be the concomitant suppression of CDK1, CDK9, c-FIP, Mcl-1 and Bcl-2 and upregulation of Bax in cancer cells." (PMID 32375399, 2020). "On the other hand, CAMK2G which is ubiquitously expressed has been shown to support cancers through activating transcription factors such as AKT1, CREB, CDK1/2." (PMID 32483123, 2020). "AURKA and AURKB also consistently scored high across every cancer cohort, as did other cell-cycle- and mitoses-related kinases (BUB1B, BUB1, CDK1)." (PMID 33205077, 2020).
cancer (continued). "Specifically, EGFR is a widely studied oncogene with a potential role in cancer therapeutics, six are core genes (AURKA, CDK1, CDT1, PRKDC, RAD51, and XRCC2), six are potential drug targets, and five were identified as drug actionable genes." (PMID 33240468, 2020). "The continuous activation of the NF-κB pathway can increase antiapoptotic gene Bcl-2 expression, upregulate expression of proliferation-related proteins CDK1 and CDK2, and promote cell cycle, thus promoting cancer cell proliferation." (PMID 32337232, 2020). "CDK1, the only CDK that can initiate the onset of M phase mitosis, is essential for the growth of cancer cells as well as normal cells." (PMID 32331421, 2020). "We found that dual CDK1 and BET inhibition generates a synergistic effect in killing BETi-resistant cancer cells." (PMID 32575711, 2020). "And most of the 24 DEPs (CDK1, SFN, PRKAR2B, MKI67 and MDK involved in the cell cycle; LOXL2, P4HA1, P4HA2, SPRX, DES, PRPH and CALML3 involved in construction and regulation of extracellular matrix; IL33 and EHD3 may involve in immune) were linked to cancer hallmarks." (PMID 33200655, 2020). "Numerous studies have demonstrated that increasing the cells in the G2/M cell cycle contributes to the radiosensitivity of many malignant tumors, including ESCC, by down-regulating CDK1 expression." (PMID 32662828, 2020). "Accordingly, the regulation of CDK1 and the usage of CDK-inhibitors have provided encouraging results in the treatment of cancer." (PMID 32605021, 2020). "Meanwhile, CDK1, CCNA2, CCNB2, BUB1B and CDC20 were classified as cancer-related genes, and RRM2 was an FDA approved drug target." (PMID 33083112, 2020). "We also found the increased CDK1 expression in HCC samples and proved its prognostic value for cancer patients." (PMID 31886163, 2019). "We have also delineated an indispensable role for the stem cell transcription factor SOX2 in CDK1-mediated stemness and tumorigenesis by demonstrating the interaction of CDK1 with SOX2 in cancer cells." (PMID 31080551, 2019). "We further analyzed the differential expression of DPYSL4, HOMER1, ABCB6, CENPA, CDK1, STMN1 in cancer and adjacent tissues, and found that compared with adjacent tissues, the six genes in 309 HCC tissues were significantly up-regulated (P<0.01)." (PMID 31790363, 2019). "We hypothesize that, in addition to contributing to the unique activities of CDK1 as a cell-cycle regulator, the particular dynamic and plastic properties of CDK1 might also be exploited to successfully differentiate CDK1 from other CDKs in future cancer therapeutic design." (PMID 30472117, 2019). "Fortunately, our work found that CDK1 and CDK2 interact with multiple ingredients for CKI, including adenine, and macrozamin, and CKI has been shown to have therapeutic effects on cancer through inhibiting CDK2 activity." (PMID 31275410, 2019). "Recently, we have shown that CDK1 plays a critical role in stochastic stemness and tumor initiation potential through regulating SOX2 phosphorylation in multiple cancer types." (PMID 31080551, 2019). "Downstream of γH2AX, all five cancer cell lines demonstrated increased phosphorylation of CHK1 and CDK1, which provides a mechanism for the G2/M arrest following TIMELESS depletion." (PMID 30629587, 2019). "Here, we identified that expression of cyclin B1 and Cdk1, cell cycle regulatory proteins, are affected by GSK-3 inhibition in cancer cells." (PMID 31882719, 2019). "According to published reports, acquired resistance to 1PTX in cancers involves other mechanisms, including altered drug efflux, epithelial–mesenchymal transition (EMT), microtubule dynamics, cyclin-dependent kinase 1 (CDK1), and cell death signaling." (PMID 29374144, 2018). "For example, CDK1 is shown to be an inhibitor of FOXO1, which is known as a common tumor suppressor in different types of human cancer." (PMID 29861861, 2018).
cancer (continued). "KLHLs are thus intriguing genes for cancer as they can directly influence the degradation of therapeutically relevant cell cycle regulators such as Aurora Kinase, PLK1, or CDK1." (PMID 30647843, 2018). "Instead, we observed that several indirect interactions disappear in the “cancer” network, namely three indirect regulations connecting STIL protein to CCNA2, CCNE1 and CDK1." (PMID 29370181, 2018). "The most attractive inhibitors are those that target cell cyclin dependent kinases (e.g. CDK1) and aurora kinases (e.g. AURKA, AURKB), which are abundantly expressed in various cancer types." (PMID 28183295, 2017). "Among the enriched genes, CDK1 plays an important role in the cell cycle, while RB1 is a driver gene in several cancer types." (PMID 28567416, 2017). "The other distinct class includes CDK inhibitors that are more selective for CDK1 and CDK2 as well as the transcriptional CDKs (CDK5, CDK7, and CDK9), and these drugs are being more widely studied in cancers including triple-negative breast cancer." (PMID 28107181, 2017). "For example, in the cancer DEG datasets, some of these genes are central in the network and are known master regulators of cell cycle (e.g., CDK1)." (PMID 28821015, 2017). "In pathway in cancer and cell cycle, Bcl2, VEGFA, PTEN, Jun, Fos, APC2 were up-regulated and Ccna2, Cdc25a, Mcm3, Mcm6, Ccnb2, Mcm5, Cdk1, Gadd45a, Myc were down-regulated in the MMQ tumor stem-like cells." (PMID 28163656, 2017). "Dinaciclib, a potent CDK2 inhibitor (as well as CDK1, CDK5, and CDK9 inhibitor) that is currently in clinical trials for several cancers, was used to target the cyclin E/CDK2 pathway." (PMID 28107181, 2017). "This analysis has shown the presence of the CDK1 protein in LSCC and its absence or small amounts in controls derived from non-cancer tissue from the larynx or regions surrounding the larynx." (PMID 26912061, 2016). "LOX knockdown leads to G2/M phase arrest; reduced p-H3(Ser10), cyclin B1, CDK1, and Aurora B. Moreover, LOX knockdown significantly increased sensitivity of cancer cells to chemotherapeutic agents that target microtubules." (PMID 27296552, 2016). "We noticed several cell cycle related genes such as CDK1 (↑), CCND1 (↑) and SMAD3 (↓), that have been widely investigated in various cancers." (PMID 27602771, 2016). "During knock-down of Cdk1 expression, the overactivity of E2F1 increased cell death in cancer cells." (PMID 27385216, 2016). "Dinaciclib, a novel small molecule inhibitor of CDK1, CDK2, CDK5 and CDK9, is assessed in clinical trials for the treatment of several types of cancers." (PMID 25962959, 2015). "The mitotic kinase CDK1/Cyclin B being essential for viability, and capable of recapitulating the functions of the other cyclin-dependent kinases in regulating cell cycle transitions in mammalian cells is not surprisingly one of the least mutated kinases in human cancers." (PMID 25625291, 2015). "Western blotting revealed that CDK1, CDK2, CDK4 and CDK6 proteins were expressed at much higher levels in the carcinoma tissues than the matched normal tissues." (PMID 24765199, 2014). "Both CDK1 and TOP2A genes have been considered as multi-type cancer markers by a previous meta-analysis of cancer microarray data." (PMID 22952714, 2012). "CDK2 siRNA silencing and inhibition of CDK2 kinase activity using a CDK1, CDK2 and CDK9 inhibitor (AZD5438) resulted in significantly higher reduction in survival of cancer cells harbouring CCNE1 gene amplification." (PMID 22433433, 2012).
cancer (continued). "This study showed a total of five genes amoung which two genes CDK1 and TOP2A differentially expressed across five cancer types." (PMID 22952714, 2012). "Cdk4 overexpression following transfection is accompanied by concomitant increase in Cdk1 expression in RAMA37 cells and disruption of Cdk1/Cdk4 co-expression can be observed in human cancer cells undergoing spontaneous cell death." (PMID 21668989, 2011). "Consistently, after LARP6 knockdown, western blot results also showed reduced expression of Cyclin B1 and CDK1, which drive the cell cycle progression from G2 to M phase, indicating that LARP6 promotes the proliferation of TNBC cancer cells via regulation of the cell cycle progression." (PMID 40635123, 2025). "Thus, cancer cell proliferation is modulated by SP1 translocation during the cell cycle progression, orchestrated by CDK1 and PP2A." (PMID 39860065, 2025). "CDK1 has been shown to phosphorylate and regulate distinct functions of several substrates, including disruptor of telomeric silencing 1-like (DOT1L), SRY-box transcription factor 2 (SOX2), and pyruvate dehydrogenase kinase 1 (PDK1), in various cancers." (PMID 40695806, 2025). "Cancer cells rely heavily on CDKs like CDK1, CDK2, and CDK9 for uncontrolled proliferation, whereas normal cells maintain cell cycle control with minimal CDK activity, making them less susceptible to Dinaciclib-induced cytotoxicity." (PMID 40076816, 2025). "Emerging recent evidence suggests that targeting CDK1 and KIF11 could be a promising therapeutic strategy for CRC and other cancers." (PMID 40457491, 2025). "Moreover, SOX2 affects cancer cell proliferation and survival by regulating cell cycle-related genes WEE1 and cyclin-dependent kinase 1 (CDK1), making PCa cells resistant to NHRSI treatment." (PMID 40821114, 2025). "Furthermore, we observed increased expression of cyclinA2, cyclinB1 and CDK1 in invasive BC cells, in comparison to what was seen in non-invasive cells, suggesting that modulation of cyclin–CDK1 complexes might play a significant role in facilitating invasive cell migration in cancer." (PMID 40518827, 2025). "Olomoucine may limit tumor growth by blocking both CDK1 and its downstream effects on CDC20, particularly in cancers with dysregulated pathways." (PMID 39457373, 2024). "Additionally, olomoucine, by targeting CDK1 and CDC20, aligns with observed dysregulation in mitotic pathways, suggesting a strategic approach to limit cancer cell proliferation." (PMID 39457373, 2024). "Besides, the expression level of CDK1, CCNA2, CHEK1, KIF11, PLK1 and TTK was significantly elevated with cancer progression in LUAD." (PMID 38783288, 2024). "Similar to the Ep_CDK1 cluster in cancer cells, we analyzed the Fb_CDK1 cluster by transferring annotation from non-cycling fibroblast clusters." (PMID 38297291, 2024). "Adding to the activation of CDKN1A and downregulation of CDK1/CYCB1, the present data suggest a direct transcriptional dysregulation of key cell cycle and survival modulators that inhibit the proliferation capacity of cancer cells." (PMID 38166099, 2024). "CDK1, CCND1, and PCNA play distinct roles in different phases of cell cycle and have been identified as pivotal genes in the development and progression of different cancer types, including colon, liver, and gynecological tumors." (PMID 38831458, 2024).
cancer (continued). "For example, APOE, PLAU, CDK1 and MUC1 were significantly higher in TNBC tissues than in cancer-parasite tissues, whereas PDGFRB, RET, ROCK2, CCND1 and PPARA were significantly lower in TNBC tissues than in cancer-parasite tissues." (PMID 38329441, 2024). "In addition, the expression level of CDK1, CHEK1, KIF11, PLK1 and TTK was significantly elevated with cancer progression in LUAD." (PMID 38783288, 2024). "Besides, as a direct regulator of P-body formation, AJUBA is also phosphorylated by CDK1 and mitotic phosphorylation of AJUBA promotes cancer cell proliferation." (PMID 39046443, 2024). "In many previous studies HDAC inhibitors as SB have shown an influence on cell cycle regulating proteins, like p21, p27 (cyclin-CDK-inhibitors), CDK1, CDK2 (cyclin-dependent-kinases), and an induction of cell cycle arrest in G1/S and M/G2-phase in various cancer cells." (PMID 38650948, 2024). "Given that VEGF promotes the EMT process and CDK1 enhances VEGF mRNA expression in cancer cells, we speculate that the inhibition of VEGF by CDK1 may be another pathway to inhibit the invasion of OC." (PMID 37569750, 2023). "Apart from these CDK1 substrates, BCL2 apoptosis regulator (BCL2), BCL2 apoptosis regulator like 1 (BCL2L1), and dynamin 1 Like (DRP1) are phosphorylated by CDK1, mediating mitochondrial fusion and apoptosis in human cancer cells." (PMID 37311884, 2023). "The alteration frequency of CDK1 in various cancers did not vary greatly, and approximately 1.2% of patients with LUAD had genetic abnormalities, with the main types being “mutation” and “amplification”." (PMID 36950551, 2023). "It would be worthwhile testing whether M1-21 acts as an inhibitor for CDK1 or XPO1 in future studies, as it might inhibit cancers synergistically by targeting multiple oncoproteins at the same time." (PMID 37344857, 2023). "Furthermore, Wee-1 is overexpressed in most cancer cells and phosphorylation of its immediate substrate (CDC2; CDK1) will halt cell cycle progression at the G2-M phase." (PMID 37633054, 2023). "The results indicated that CCNA2, CCNB1, CDK1 and CDKN2A were expressed in cancer epithelial cells." (PMID 37265472, 2023). "Interestingly, upregulation of CDK1 and CDK4 is correlated with poor prognosis in cancer patients, especially in those with resistance to 5-FU46–48." (PMID 37328457, 2023). "It remains to be seen whether redundancies in the CDK2/CCNE1 pathway (CDK1 for CDK2, CCNE2 for CCNE1) observed in normal cells pose another challenge of targeting this pathway in cancers." (PMID 36572991, 2023). "CDK1 is the mitotic CDK that functions to control several important steps of prior to cell division, and has been reported as a target for therapy for various cancers." (PMID 36769170, 2023). "The prognostic value of CDK1 across cancers was analyzed using GEPIA2.0, and the results indicated that patients with various cancers, such as kidney renal clear cell carcinoma, brain lower grade glioma, liver hepatocellular carcinoma, and LUAD, with high CDK1 expression tended to have shorter OS." (PMID 36950551, 2023). "PPI interaction network analysis showed that the CCNF gene, CDK1 gene and CDC6 gene are closely related, indicating that these genes, as key regulators of the G2/M or G1/S checkpoint of the cell cycle, promote the occurrence and progression of many cancers." (PMID 37168372, 2023). "Because HDAC3 has been reported to regulate the phosphorylation of STAT3 Y705 in other cancer types, we speculated that HDAC3 might influence the phosphorylation of STAT3 Y705 via activation of CDK1." (PMID 37743465, 2023). "Indeed, several previous studies in human immortalized or cancer cells have suggested a function of ATR and CHK1 in controlling replication initiation and origin firing by counteracting CDC7 or CDK1 activties." (PMID 37336885, 2023). "For example, TPRGs CDK1 and CXCL12 are expressed in both T cells and various cancer cells." (PMID 37077919, 2023).